VIP (vasoactive intestinal peptide)
Diseases named in the same sentence as VIP in open-access papers (continued):
Sharing a sentence is not in itself a finding about the gene and the disease.
asthma (32 papers, 2008 to 2025). "It is recognized that the onset of asthma and airway responsiveness were closely associated with decrease of vasoactive intestinal peptide (VIP), which influenced the endogenous oxidant/antioxidant balance and the relaxation of the intestine." (PMID 23970934, 2013). "Future studies using human tissue and cells need to be performed in order to further elucidate the role of VIP on mucus secretion that associated with hypersecretory diseases such as COPD or asthma." (PMID 21477377, 2011). "With oxidants including reactive oxygen species being implicated in the pathogenesis of asthma, VIP's mechanism of action in reversing the asthma phenotype would be its anti-oxidant effect." (PMID 22103391, 2011). "Some evidence suggests a functional loss of VIP-innervation to the airways in asthma, although this may be secondary to inflammation." (PMID 30081920, 2018). "Using a combination of genomics and proteomics methodologies, we aimed to determine if genes and their proteins implicated in the pathogenesis of asthma, such as anti-oxidant proteins, are modulated by the VIP gene, suggesting a mechanism of anti-asthma action by VIP." (PMID 22103391, 2011). "Aviptadil acetate is a synthetic form of human vasoactive intestinal peptide that exerts anti-inflammatory activities, especially in the lung and has been used to treat inflammatory conditions such as asthma and acute respiratory distress syndrome." (PMID 40277885, 2025). "For example, vasoactive intestinal peptide (VIP) is involved in promoting allergic inflammation in asthma by acting on ILC2 and Th2 cells." (PMID 38433844, 2024). "Sensory neurons expressing TRPV1 and/or voltage‐gated sodium channel Nav1.8 produce neuropeptides such as CGRP, vasoactive intestinal peptide (VIP) and substance P, which participate in the formation of asthma." (PMID 39129233, 2024). "In response to asthma, sensory neurons release substance P. Administration of VIP into sensory neuron-depleted mice suppresses bacterial burden, while VIPR1 deficiency increases infection." (PMID 39414787, 2024). "Asthma symptoms were relieved after intraperitoneal injection of VIP, indicating that VIP plays an anti-inflammatory role in the development of asthma." (PMID 38331782, 2024). "The lungs have a dense network of nociceptors expressing sensory neurons, which produce VIP and exacerbate asthma symptoms by activating T cells and ILC2s via the VIP–VIP receptor type 2 axis." (PMID 36941691, 2023). "In 2003, Linden and colleagues examined the effects of a VIP agonist in asthma and found a short, but effective, bronchodilatory effect." (PMID 30081920, 2018). "Anti-VIP Abzs can have poor effect on pathogenesis due to a reduction in the concentration of VIP playing an important role in the asthma pathophysiology." (PMID 29410824, 2018). "Perhaps a renewed interest in VIP analogs will reinvigorate efforts to examine their therapeutic potential in asthma." (PMID 30081920, 2018). "It is unnecessary to use allergic sensitization to induce these asthmatic changes, making the VIP mouse model a unique genetic asthma phenotype." (PMID 22126441, 2011). "In fact, the asthma pathology worsens with age in VIP KO mice, leading to increased inflammation over time which is also consistent with an accumulation of abnormal isomer with age." (PMID 22103391, 2011). "VIP KO mice have recently been demonstrated to have spontaneous airway and pulmonary perivascular inflammatory responses, as part of asthma-like and pulmonary hypertension phenotypes, respectively." (PMID 22126441, 2011). "Increased levels of dihydropteridine reductase would be consistent with increased endogenously produced NO by mast cells, which is consistent with the spontaneous high IgE levels in VIP KO mice and the asthma phenotype (Szema, unpublished data)." (PMID 22103391, 2011). "Similarly, DPI formulations containing mometasone furoate and VIP derivatives provide targeted management of asthma and COPD." (PMID 40005989, 2025).
asthma (continued). "Vasoactive intestinal peptide (VIP) is abundant in healthy lung of tissue, modulating immune responses and exerting anti-inflammatory effects by interacting with specific receptors on immune cells; thus, VIP functions as a potent anti-inflammatory mediator in asthma." (PMID 41573715, 2025). "In asthma, allergen stimulation triggers VIP release from sensory neurons." (PMID 41415714, 2025). "Plasma VIP levels change significantly during asthma exacerbations." (PMID 41415714, 2025). "In addition, M-BYF was also found to alleviate AHR, airway inflammation and remodeling in asthma mice by negatively regulating the vasoactive intestinal peptide-vasoactive intestinal peptide receptor type 2 (VIP-VPAC2) signaling pathway." (PMID 38590639, 2024). "Similarly, low concentrations of vasoactive intestinal peptide or VIP mediate asthma pathology following interaction with one of its receptors, VPAC2." (PMID 39007622, 2024). "Vasoactive intestinal peptide (VIP), a vasoactive mediator, present in the neuroendocrine cells of the airway epithelium, is released along with other neuropeptides and neurotransmitters following exposure to the allergen in asthma." (PMID 37240671, 2023). "VIP plays a key role in allergic diseases like AR and asthma." (PMID 32798199, 2022). "Moreover, the administration of experimental agents such as NK1R/NK2R antagonists and exogenous VIP decrease inflammatory mediators, suggesting that regulating the effects of NT/NP represents a potential novel approach for the treatment of asthma." (PMID 34055794, 2021). "Although speculative, this finding might suggest that VIP has an inhibitory role on muc5AC expression in asthma." (PMID 30081920, 2018). "A larger variation in right ventricle dimensions compared to that of the left ventricle may result from the heterogeneity in expression of the asthma phenotype that is seen among the homozygous VIP knockout mice." (PMID 23700405, 2013). "Recently, attention has been drawn to the therapeutic potential of VIP for the clinical treatment of COPD/asthma on the basis that VIP acts as a neurotransmitter, the dominant mechanism of human airway and vascular relaxation, and its anti-inflammatory properties." (PMID 21477377, 2011). "One potential implication is that VIP and its analogues may be used to treat inflammatory diseases, including asthma." (PMID 22103391, 2011). "Although we were not able to find any studies concerning the effects of VIP on muc5B regulation and/or expression in asthma, since muc5B might be decreased in asthma, and VIP might also be decreased, then one speculation is that VIP directly stimulates production of muc5B." (PMID 30081920, 2018). "Moreover, asthma-related in vivo upregulation of pro-inflammatory neurokinin 1 and neurokinin 2 receptors was counteracted by MSCs that also determined a partial restoration of VIP, a neuropeptide with anti-inflammatory properties." (PMID 27434719, 2016). "Recent work has proposed VIP, one of the major peptide transmitters in the central and peripheral nervous system, as a promising agent for the treatment of chronic airway disease including asthma and COPD based on its combined bronchodilatory and immunomodulatory properties." (PMID 24069452, 2013). "The following three protein were upregulated in VIP KO mice and may modulate the asthma phenotype:." (PMID 22103391, 2011). "Neuropeptides and neurotransmitters, such as vasoactive intestinal peptide (VIP) and neuromedin U, have been shown to activate ILC2s in mouse models of asthma." (PMID 40355861, 2025). "For instance, vasoactive intestinal peptide (VIP) derivatives, such as IK312532, have demonstrated enhanced anti-inflammatory efficacy in asthma and chronic obstructive pulmonary disease (COPD) models when delivered via DPIs with reduced systemic side effects." (PMID 40005989, 2025).
asthma (continued). "The results confirmed that after stimulating the large intestine by Mangxiao or Dahuang, SP, NK1R, VIP, VIPR1, and VIPR2 were all significantly increased in large intestine tissue of rats with COPD and mice with asthma." (PMID 24023578, 2013). "This article describes the physiological significance of VIP and its therapeutic potential for the treatment of cardiopulmonary diseases, including PAH, asthma, and COPD." (PMID 21477377, 2011). "VIP exerts functions not only as a vasodilator and bronchodilator but also as a potent immunomodulator, thus VIP has significant therapeutic potential in the treatment of pulmonary diseases, including: PAH, asthma and COPD." (PMID 21477377, 2011). "VIP has emerged as a promising drug candidate for the treatment of cardiopulmonary disorders such as PAH, asthma, and COPD." (PMID 21477377, 2011). "Recent studies show that inhalable powder formulation of VIP derivative, IK312532 attenuates airway inflammation in ovalbumin challenge-induced asthma/COPD -like rats and in cigarette smoke-exposed rats." (PMID 21477377, 2011). "The development of long-acting VIP analogues, in combination with appropriate drug delivery systems, may provide clinically useful agents for the treatment of PAH, asthma, and COPD." (PMID 21477377, 2011). "With the use of VIP KO mice we demonstrated that VIP replacement attenuated the asthma phenotype but had not yet delineated a VIP's mechanism of action." (PMID 22126441, 2011). "We showed earlier that mice lacking the gene for VIP have spontaneous features of asthma, with airway inflammation (peribronchiolar lymphocytes and eosinophils) and pro-inflammatory cytokine production in bronchoalveolar lavage fluid--yielding IL-5 and IL-6." (PMID 22126441, 2011). "We earlier reported that mice lacking VIP have the spontaneous asthma phenotype: 1) peribronchiolar airway inflammation with lymphocytes and eosinophils, and 2) airway hyper-responsiveness to inhaled methacholine." (PMID 22103391, 2011). "The development of long-acting VIP analogues, in combination with appropriate drug delivery systems, may provide clinically useful agents for the treatment of PAH/asthma/COPD." (PMID 21477377, 2011). "In terms of neuroimmune interactions, IL‐5 from ILC2 and CD4+ T cells directly stimulates VIP secretion from pulmonary nociceptors, and VIP in turn activates ILC2 and CD4+ T cells, forming a positive feedback loop that amplifies Type 2 inflammation in OVA‐ and HDM‐induced asthma mouse models." (PMID 41415714, 2025). "Vasoactive intestinal peptide (VIP) plays diverse and important role in human physiology and physiopathology and their receptors constitute potential targets for the treatment of several diseases such as neurodegenerative disorder, asthma, diabetes, and inflammatory diseases." (PMID 23115557, 2012). "Studies using VIP deficient animals and using animal models of diseases have indicated that VIP has significant therapeutic potential in the treatment of cardiopulmonary diseases, including pulmonary arterial hypertension (PAH), chronic obstructive pulmonary disease (COPD) and asthma." (PMID 21477377, 2011). "Although we did not test the function of lung carbonyl reductase in VIP KO mice, this different form may have a bearing on function since the asthma phenotype is present despite strong expression of the isomer." (PMID 22103391, 2011). "Therefore, development of drug delivery system for VIP-based respiratory therapy may be a promising strategy for the treatment of PAH, asthma and COPD." (PMID 21477377, 2011). "VIP therefore appears to contribute to modulation of the oxidant/antioxidant balance in asthma, since wild-type mice with VIP have functional lung carbonyl reductase and no spontaneous asthma, whereas VIP KO have abnormal carbonyl reductase and have spontaneous asthma." (PMID 22103391, 2011).
asthma (continued). "Therefore, the development of long-acting VIP analogs with strong bronchodilatory effects or modulators of the VIP-VPAC2 signaling pathway may provide clinically useful agents for the treatment of asthma." (PMID 34948451, 2021). "Abnormal secretion of SP and VIP could be observed in other organs such as stomach tissues of rats or heart and stomach tissues of mice; however, the receptors did not change obviously, while the NKA and NKB levels were similar in lung tissues of mice with asthma among groups." (PMID 24023578, 2013). "Since our mice have the spontaneous asthma phenotype, and asthma and its exacerbations are associated with oxidation and reactive oxygen metabolites, then an alteration in the isomeric make-up of anti-oxidant proteins could explain why this asthma in VIP KO mice does not spontaneously resolve." (PMID 22103391, 2011). "In our model, nociceptor neuron ablation diminishes γδ T cell activation, which we posit is chiefly driven by SP/VIP, given the absence of heightened CGRP release in our asthma models." (PMID 39229121, 2025).
Arthritis (22 papers, 2005 to 2022). Inflammation of a joint. "In this sense, we earlier demonstrated the association between serum VIP levels and an allelic variant in VIP gene in patients with early arthritis through a miRNA-mediated mechanism." (PMID 35955723, 2022). "To this end, we evaluated the serum levels of molecules implicated in resorptive activity in early arthritis patients with high and low serum VIP levels." (PMID 34944693, 2021). "Elevated serum VIP levels in early arthritis patients were associated with lower BMD loss and higher serum OPG concentration." (PMID 34944693, 2021). "In this regard, to our knowledge, this study is the first to demonstrate that several polymorphisms of the VIP gene are associated with differences in serum levels in patients with early arthritis." (PMID 29391448, 2018). "Moreover, we have reported cases of early arthritis where combinations of genetic variants of VIP gene were associated with treatment requirements." (PMID 35955723, 2022). "Moreover, we further found that early arthritis patients with elevated serum VIP levels exhibit lower BMD loss, a clinical marker for bone strength that has been associated with joint damage in RA." (PMID 34944693, 2021). "Variables associated with VIP serum levels during follow-up of patients with early arthritis." (PMID 24409325, 2014). "Since a pioneering study demonstrated the beneficial role of VIP in a murine arthritis model, downregulating both the inflammatory and the autoimmune components of the disease, different studies valued its therapeutic potential." (PMID 34208590, 2021). "We also investigated the relationship between VIP serum levels and bone remodeling mediators in early arthritis patients." (PMID 34944693, 2021). "The main receptor involved in VIP effects on arthritis is VPAC1, as demonstrated by the use of specific agonists in arthritic mice." (PMID 31695683, 2019). "Given these concerns, we have recently described the utility of measuring VIP as a clinical biomarker in patients with early arthritis (EA)." (PMID 31695683, 2019). "In this regard, we have recently reported that patients with Early Arthritis (EA) and early Spondyloarthritis (SpA) who displayed low VIP serum levels at disease onset appeared to develop a greater burden of disease." (PMID 29391448, 2018). "Healing effects of exogenous administration of VIP in animal models of inflammatory/autoimmune diseases have been described; specifically, VIP prevents arthritis in a CIA model through its anti-inflammatory and immunomodulatory actions." (PMID 30155495, 2018). "VIP actions indicate an anabolic function in the skeletal system and protective effects of VIP application preventing destruction of bone and cartilage have been demonstrated in collagen-induced murine arthritis." (PMID 28452955, 2017). "Usually the inflammatory neuropeptides substance P, calcitonin gene-related peptide, as well as VIP, have all been reported to be immunolocalized in joint tissues and their levels are increased in arthritis." (PMID 27553659, 2016). "VIP is reported to be localized in postganglionic sympathetic and sensory nerve fibres that are in close proximity to the synovial fluid and serum of arthritis patients." (PMID 27553659, 2016). "We recently reported promising findings about the role of endogenous VIP in early arthritis (EA), showing that patients with low baseline VIP levels have worse disease outcome." (PMID 26881970, 2016). "Treatment with VIP has been shown to reduce the severity of arthritis in murine models and improves the course of other inflammatory models in mice." (PMID 25711477, 2015). "We recently reported that early arthritis patients with low baseline serum VIP levels have a more severe disease course and require more intensive treatment with disease-modifying anti-rheumatic drugs (DMARDs)." (PMID 25711477, 2015).